SOX2 (SRY-box transcription factor 2)
Diseases named in the same sentence as SOX2 in open-access papers (continued):
Sharing a sentence is not in itself a finding about the gene and the disease.
cancer (continued). "In BCa cells, our findings demonstrate that TACO1‐mediated OXPHOS increases mtROS, a major source of intracellular ROS, thereby promoting cancer cell stemness and cisplatin resistance via SOX2 upregulation." (PMID 39656941, 2025). "In UC, SOX2 expression is suggested to be a marker for a subpopulation of cancer stem cell (CSCs) that co-express keratin 14 (KRT14) and CD44v6, and these CSCs are responsible for the maintenance, invasion, and progression of UC tumors." (PMID 40643470, 2025). "Although numerous reviews have addressed the role of the SOX family in cancers such as ovarian, cervical, and gastric cancer, a notable gap remains in the literature concerning the role of SOX2 in PCa." (PMID 40821114, 2025). "Although SOX2 traditionally serves as a marker for maintaining stemness, its role in oncogenesis remains debated across different cancers." (PMID 40133476, 2025). "The system also enriched cancer stem-like properties, with higher expression of stemness-associated genes (CD24, CD44, CD133, ALDHA1, CXCR4, Sox2, Oct4, Nanog, and KLF4) and expansion of CSC populations expressing (CD44, CD90, CD117, EpCAM, and CK19)." (PMID 41149589, 2025). "Analyses of known genes involved in progression and differentiation in tumor gene expression studies have revealed that SOX2 is overexpressed in poorly differentiated cancer subtypes." (PMID 40104101, 2025). "In the present study, COL1A1 silencing in KIRC cells was associated with reduced expression of the stemness markers OCT4 and SOX2, supporting a possible involvement in the maintenance of cancer stem cell properties." (PMID 40851082, 2025). "Regarding cancer stemness, Ad-VP3 significantly impaired sphere-forming capacity and reduced the expression of stemness-associated proteins ALDH1A1, KLF4, and Sox2 in a time-dependent manner at 48 h and 72 h post-infection." (PMID 41472305, 2025). "In stem cell and cancer stem cell (CSC) research, OCT4 and SOX2 are pivotal transcription factors linked to pluripotency." (PMID 40004228, 2025). "Supporting our findings, a recent study in MM showed that NA reduces the side population and expression of the cancer stem cell core genes Nanog, Oct-4 and Sox-2 in HMCLs." (PMID 40241199, 2025). "Complementing this pathway, the stemness factor SOX2 maintains cancer cell plasticity and therapy resistance through regulation of stem cell markers including CD44 and OCT4." (PMID 40508204, 2025). "In this line of thinking for EBVaGC, MUC1-C was necessary for upregulation of the (i) SOX2 and KLF4 genes, which are linked to cancer progression, and (ii) NOTCH genes that drive stemness." (PMID 40764753, 2025). "The SOX2 gene, amplified in ~50% of patients, plays a critical role in sustaining the cancer phenotype." (PMID 41388088, 2025). "Our data indicate that a chemoresistant cancer cell population, which acts as a reservoir for resistant tumors, exhibits characteristics typical of cancer stem cells (CSCs) and is marked by SOX2 expression." (PMID 39994220, 2025). "SOX2 has also been reported to promote maintenance of cancer stem cell (CSC) phenotypes, including in CRC." (PMID 40179020, 2025). "Western blot analysis revealed that CCT-031374 suppressed the 231-RR-EV-induced upregulation of cancer stemness proteins, including c-Myc and SOX2 in both 231-P and Hs578T cells." (PMID 40657369, 2025). "SOX2 was proposed to promote metastasis, and its amplification was observed in several cancer types." (PMID 40276932, 2025). "The expression of EMT inducing transcription factors such as ZEB1, SNAIL1 and 2 by cancer cells initiates the expression of stem cell markers SOX2, BMI1 and OCT4." (PMID 41190163, 2025). "Western blot analysis further revealed that RR-GW-EVs failed to upregulate the active form of β-catenin, as well as other cancer stemness proteins of c-Myc and SOX2 in 231-P cells." (PMID 40657369, 2025). "The expression levels of cancer stem cell-associated genes STAT3, SOX2, and MYC, varied among cancer cell clusters." (PMID 40883281, 2025).
cancer (continued). "As the second member of the SOX family, SOX2 is one of the most extensively studied members and plays a crucial role in various cancer types." (PMID 40821114, 2025). "Consistent with RNAi results, infection with GATAD2B gRNA reduced GATAD2B levels and levels of cancer stem-like cells markers SOX2 and c-Myc, and significantly reduced mammosphere formation when compared to control gRNA." (PMID 40136647, 2025). "It was also suggested SOX2 mediates these effects by modulating Wnt pathway signaling and β-catenin levels in cancer cells." (PMID 40179020, 2025). "Stemness of cancer stem cells (CSCs) is associated with expression of the Yamanaka OCT4, SOX2, KLF4 and MYC (OSKM) pluripotency factors that confer lineage plasticity and dedifferentiation." (PMID 40764753, 2025). "Met also significantly decreased the expression of pluripotency transcription factors (Oct‐4, Sox2 and Nanog), indicating its potential to target cancer stem cells (CSCs)." (PMID 40387464, 2025). "Transcription factors such as NANOG, OCT4, and SOX2 are overexpressed in several cancers, including liver, squamous, lung, brain, colon, and breast cancers." (PMID 40647402, 2025). "SOX2 (sex-determining region Y-box 2) is a well-characterized pluripotent factor, and has been identified as an anti-cancer target, which is crucial for stem cell self-renewal, reprogramming, and homeostasis." (PMID 39991565, 2025). "Our results showed that ALDH1, CD44, Sox2, Olig2, BMI1, LGR4, LGR5, Integrin α6, L1CAM, and ABC transporter associated with cancer stem cells were significantly downregulated." (PMID 39721005, 2025). "Here, we uncover the pivotal role of the PRMT1/SOX2 axis in regulating cancer stemness, a key factor contributing to cancer chemoresistance." (PMID 41377018, 2025). "SOX2 functions in the CSCs’ self-renewal and stemness maintenance in invasive cancer types, and its depletion inhibits cancer invasion in cancers including BCa." (PMID 41145440, 2025). "TGF-β can activate the AKT pathway, leading to increased expression of cancer stem cell markers (SOX2, ABCG2) and cisplatin resistance." (PMID 40486962, 2025). "Metavert treatment of human organoids also strongly downregulated mRNA and protein levels of the cancer stem cell markers CD44 and SOX2 associated with EMT and chemotherapy resistance." (PMID 39217851, 2024). "Sox2 has emerged as a crucial factor in cancer progression, showing aberrant expression in various human cancers, including CRC." (PMID 38473392, 2024). "The precise role of HAR1B still needs to be elucidated; nonetheless, it has been found to be upregulated in cancers and likely induces SOX2 expression in PAd-derived cells." (PMID 39409111, 2024). "The discovery of six amplified (i.e., WHSC1L1, CCND1, and SOX2) and 29 deleted (i.e., NCOR1, SETD2, and CBL) cancer associated genes was highlighted." (PMID 38539567, 2024). "As a result, we find an increase in the fraction of stem-like cells expressing cancer marker, SOX2, within polyps compared to FAP mucosa." (PMID 39605357, 2024). "For instance, additional analysis involving stemness markers such as Nanog, OCT-4, and SOX-2 is needed to further elucidate the impact of WWTR1-AS1 on cancer cell stemness." (PMID 38331752, 2024). "Historically, Sox2 has been shown to control cancer stem cell maintenance and self-renewal, fostering oncogenic signaling." (PMID 38540701, 2024). "Reduced miR-744 expression, by stimulating the SOX2/Wnt/β-catenin signaling pathway, stimulates the proliferation, migration and invasion of MM cells, influencing the development and progression of cancer." (PMID 38473390, 2024). "Recently, several phase I and II clinical trials (NCT05242965, NCT05455658, NCT02157051) have commenced for STEMVAC, a DNA plasmid-based vaccine that targets multiple cancer antigens, including SOX2." (PMID 38612911, 2024).
cancer (continued). "This highlights the role of miRNAs in the post-transcriptional regulation of Sox2 and adds to the understanding of Sox2 regulation in cancer progression." (PMID 38473392, 2024). "Numerous studies have identified the role of PI3K signaling in cancer stemness, affecting markers such as Nanog, SOX2, and CD133." (PMID 39394200, 2024). "SOX2 is considered undruggable; however, several approaches have been administered to target SOX2 for cancer therapeutics, as reviewed by Zhang and colleagues." (PMID 38674385, 2024). "Overexpression and amplification of SOX2 have been observed in many types of tumors, leading to accelerated migration, proliferation, invasion, and metastasis of cancer cells, ultimately resulting in resistance to apoptosis." (PMID 39062149, 2024). "This emphasizes the necessity of considering cancer subtype-dependent and context-dependent factors when targeting SOX2 overexpression as a potential therapeutic vulnerability in diverse cancers." (PMID 38334608, 2024). "SOX2 is involved in many cancer pathways, and the PI3K/Akt/mTOR pathway has been shown to positively regulate SOX2 expression." (PMID 38612911, 2024). "Consistent with previous studies that an EMT-TF Zeb1 controls the stemness of neural stem cells as well as cancer initiating cells, Zeb1 expression was found in many Sox2+ neural stem/progenitors in the VZ of DG at E14 (Figures 2A1–A8)." (PMID 39268037, 2024). "An increase in Sox2 expression is observed in various types of cancer, determining the proliferation, migration, invasion, and metastasis of cancer cells." (PMID 38664641, 2024). "The SOX gene family, particularly SOX2, plays a significant role in carcinogenesis, maintaining cancer stem cell (CSC) pluripotency and regulating cell differentiation, proliferation, and survival." (PMID 38927713, 2024). "Sox2 exerts pleiotropic effects on cell identity, and its roles in the development and cancer across different organs have been reported." (PMID 38182591, 2024). "The targeting of epigenetic mechanisms to repress SOX2 has also been investigated as an anti-cancer mechanism." (PMID 38612911, 2024). "Previous findings suggested that the down-regulation of SOX-2 significantly induces apoptosis in various cancer types, including BC." (PMID 38864530, 2024). "SOX2 is over-expressed in many poorly differentiated and aggressive cancers, including breast, ovarian, gastric, and colon carcinomas." (PMID 38396925, 2024). "SOX2 on the other hand, has an unexpected role since the loss of its expression enhances both self-renewal and EMT, two well-known processes that drive cancer progression." (PMID 38951654, 2024). "Furthermore, combined amplification of PIK3CA and SOX2 is emerging as a valuable and easy-to-implement tool for cancer risk stratification that may complement histopathological diagnosis to distinguish high-risk patients more accurately, and to ultimately improve personalized treatment decisions." (PMID 38473941, 2024). "What is interesting, it that it was also proven that SOX2 was involved in the resistance of cancer cells to different anticancer therapies, such as chemotherapy, radiotherapy and targeted therapy." (PMID 39272712, 2024). "Subsequently, we examined the expression of CD44v6, a key cell surface marker for cancer stem cells, and the self-renewal proteins SOX2, Nanog, and Oct4 in MKN45, MKN74, and NUGC4 cells after being co-cultured with ASCs or cultured alone." (PMID 39766174, 2024). "SOX2 enhances mesenchymal gene activation while suppressing epithelial genes that enable EMT-induced cancer cell spread." (PMID 38532463, 2024). "SOX2 expression is commonly detected in multiple cancer types and found to positively regulate tumor cell proliferation, migration, invasion, and metastasis." (PMID 38473941, 2024). "The identification of m6A methylation as a key mechanism in stabilizing SOX2 mRNA underscores the importance of posttranscriptional modifications in cancer biology." (PMID 39445001, 2024).
cancer (continued). "In general, Sox2 is known to promote proliferation, invasion, metastasis, stemness, and drug resistance in cancer cells, making it an attractive target for anticancer therapies." (PMID 38473392, 2024). "A study investigating the link between PI3K signalling and cancer stem cell activity found that the PI3K/mTOR pathway is a direct regulator of SOX2 expression in colorectal CSCs." (PMID 38920995, 2024). "Together, this is indicative that growth factor receptor inhibitors decrease stem cell capabilities in multiple SOX2-driven cancer types." (PMID 38612911, 2024). "Altogether, the results presented here demonstrate that a prominent SOX2 expression was only detected in cancer cells, while SOX9 expression was also detected in stromal cells of the TME." (PMID 38275880, 2024). "SOX2-induced inhibition of Notch pathway in NOTCH-driven TNBC is associated with EMT and cancer stem cell features." (PMID 39478150, 2024). "SOX2, a member of the SOX B1 group, has garnered significant attention as a prognostic, diagnostic, and therapeutic target in various cancer types." (PMID 38927713, 2024). "In summary, our work demonstrates the role of two relevant genes (DUSP1 and SOX2), in a rare type of cancer such as SG-SCC." (PMID 38951654, 2024). "Paclitaxel-treated cancer cells show stronger expression of stem-associated ALDH2, SOX2, and Nanog markers than untreated cells." (PMID 39062149, 2024). "Analysis of SOX2 KO RNAseq threw some light into the functions that SOX2 is controlling in these cancers." (PMID 38951654, 2024). "Cytoplasmic Oct4, Nanog, and Sox2 observed in the inner cells of the small cysts are reportedly expressed in cancer stem cells, zygotes, and blastomeres." (PMID 38892233, 2024). "Recent studies have revealed that SOX2, a pluripotent stem cell factor, significantly contributes to cancer stem cell (CSC)-like characteristics closely associated with cancer malignancy." (PMID 38334608, 2024). "Hypoxia is believed to have impact on cancer stem cell (CSC) phenotype and leads to dysregulation of cancer stemness transcription factors such as Sox2 and Nanog." (PMID 38016355, 2024). "Key signaling pathways, including TGF-β and Wnt/β-catenin, and transcription factors like Snail and SOX2, drive this interplay, complicating cancer treatment." (PMID 39403386, 2024). "The in vitro study of the signaling chain whereby RAB4A impacts cancer cell stemness has demonstrated that NUMB, NOTCH1, RAC1, and SOX2 are essential in mediating the regulatory effects of RAB4A on CSCs in multiple cancer cell lines of diverse tissue origins." (PMID 39463384, 2024). "Stem cell transcription factor SOX2 endows cancer cells with resistance to ferroptosis by activating SLC7A11." (PMID 38739940, 2024). "KLF8 directly binds the promoter region of miR‐429 to inhibit its expression, which targets SOX2 to mediate cancer stem cell‐like features in CD133+ OSCs." (PMID 39263604, 2024). "SOX2’s capacity to regulate self-renewal and its cross-talk with other signaling pathways is co-opted in numerous cancer types." (PMID 39095874, 2024). "In conclusion, these studies in both RAB4A-high and RAB4A-low cancer cells demonstrate that RAC1 is upstream of SOX2 in the RAB4A regulation of cancer stemness, while the order of regulation among RAC1, NUMB, and NOTCH1 are yet to be defined." (PMID 39463384, 2024). "Limited data regarding the correlation of STIM1 and SOX2 in cancer and their possible synergistic impact." (PMID 38532463, 2024). "Many studies report the role of the CSC marker SRY-box 2 (SOX2) not only in CSC formation but also in cancer cell proliferation, migration, invasion, and drug resistance." (PMID 38827317, 2024). "Numerous studies have reported that SOX2 plays an important role in the development of various human cancers." (PMID 38879516, 2024).
cancer (continued). "Oct4, Sox2, c-Myc and Klf4 had been identified as cancer stem cell (CSCs) markers, playing a key role in the reprogramming of somatic differentiated cells into induced pluripotent stem cells (iPSCs)." (PMID 38822350, 2024). "The expression of SOX2 in the cytoplasm indicates the aggression of cancer cells and the ability to survive applied stress." (PMID 39062149, 2024). "For example, rare cancers such as gliomatosis peritonei can be detected by identifying high expression of the stem cell marker Sox2 and low expression of the transcription factors Oct4 and Nanog." (PMID 38256274, 2024). "Past research had revealed that Sox2 exerts in oncogenesis, reprogramming, and diverse cancers, especially in caner stem cells." (PMID 37749430, 2024). "Depletion of SOX2 within melanoma cell populations expressing the cancer stem cell marker aldehyde dehydrogenase 1 limits their tumorigenic capacity and clonogenicity." (PMID 39095874, 2024). "SOX2-expressing cancer cells usually act as cancer progenitor/stem cells that are resistant to various cancer therapeutic compounds." (PMID 38396925, 2024). "We compared expression differences of traditional cancer stem biomarker Sox2, Nanog and MACC1 between the two cultured conditions." (PMID 39695175, 2024). "In LUAD, there is a report showing that SOX2 promotes the growth of spheroids and confers cancer drug resistance in A549 cells." (PMID 38334608, 2024). "In summary, these studies conclude that NOTCH1, through its activation product NICD, forms a necessary link in the RAB4A signaling axis upstream of RAC1 and SOX2 in promoting the cancer cell stemness/self-renewal property." (PMID 39463384, 2024). "Using in vitro and in vivo studies, we show that RAB4A, as the upstream regulator, relays signal stepwise to NUMB, NOTCH1, RAC1, and then SOX2 to control the self-renewal property of multiple cancer cells of diverse tissue origins." (PMID 39463384, 2024). "As both AURKA and SOX2 are overexpressed in numerous cancers, the impact of their potential crosstalk on aggressive oncogenic phenotypes remains a subject of huge interest." (PMID 39334449, 2024). "Major pluripotency TFs like Sox2 are important for facultative stem cell plasticity in normal tissue while also driving cancer phenotypic plasticity." (PMID 40994652, 2024). "We analyzed changes in the mRNA expression levels of core factors of cancer and stem cell-related Oct4, Sox2, and Nanog and angiogenesis-related VEGF 188, after exposure to RT by an RT–qPCR analysis." (PMID 39272290, 2024). "Activation of Sox2 enhances the proliferation of cancer cells and it is important for the function of the lung CSCs." (PMID 38664641, 2024). "We explored the correlation between SOX2 expression levels and the molecular subtypes of different cancers." (PMID 38164286, 2024). "Since it has been reported that the overexpression of SOX2 renders A549 cells resistant to cancer drugs, cisplatin and paclitaxel, we performed drug sensitivity assays of gMock and gSOX2 LUAD cells using the cancer drugs." (PMID 38334608, 2024). "GSCs showed characteristics consistent with cancer stem cells: namely, neurosphere formation; expression of stem cell markers Sox2 and OLIG2 and multilineage differentiation with markers for astrocytes (GFAP), neurons (MAP2) or oligodendrocytes (O4)." (PMID 37997289, 2024). "These compounds were also shown to reduce stemness markers, namely, CD133, NANOG, MgSOD, and SOX2, in various in vitro and in vivo cancer models, with implication of c-Met signalling inhibition in the mechanism of action." (PMID 38612718, 2024). "Here we showed reduced mRNA and protein levels in the cancer stemness markers Sox2 and CD44 in the organoids following Metavert treatment." (PMID 39217851, 2024). "Current studies have reported that Sox2 can participate in the regulation of cancer proliferation, migration, invasion and metastasis through transcriptional regulation and other gene expression." (PMID 39605920, 2024).